SP1 (Sp1 transcription factor)
Diseases named in the same sentence as SP1 in open-access papers (continued):
Sharing a sentence is not in itself a finding about the gene and the disease.
gastric cancer (continued). "Although Sp1 is a common TF, Sp1‐dependent transcription is highly regulated and heavily involved in the development of various cancers, including lung 14 and gastric cancer." (PMID 26763486, 2016). "The overexpression of Sp1 is considered a prognostic indicator for the poor survival of gastric cancer patients." (PMID 26511642, 2016). "Another study showed miR-22 acts as tumor suppressor by targeting the Sp1 gene and inhibiting gastric cancer cell migration and invasion." (PMID 26512777, 2015). "Dysregulation of SP1 is found in many types of cancer, including ovarian, breast, and gastric cancer, for which HB-EGF is a rational therapeutic target 22,29,30." (PMID 25060396, 2014). "MTA2 expression was positively correlated with transcription factor Sp1 in gastric cancer tissues (r = 0.326, P < 0.001)." (PMID 24010737, 2013). "The percentage cases with high SP1 expression in intestinal-type gastric cancer was significantly reduced in the distant metastasis group (P = 0.008)." (PMID 23437057, 2013). "Administration of sub-cytotoxic (0.1 and 0.2 mM) MJ resulted in a decrease in the Sp1 expression in gastric cancer SGC-7901 and MKN-45 cells." (PMID 23394613, 2013). "Meanwhile, our previous study had showed that Bcl-w-induced Sp1 expression contributed to invasiveness by activating MMP-2 in gastric cancer cells." (PMID 23826359, 2013). "We examined SP1 expression and the clinical significance of its relationship with Lauren's histological classification of the different types of gastric cancer tissue samples and cell lines." (PMID 23437057, 2013). "Sp1 was found to be overexpressed in gastric cancer tissues, and had positive correlation with MTA2." (PMID 24010737, 2013). "As observed in the Kaplan-Meier curves, the univariate analysis indicated an inverse relationship between SP1 expression and patient survival in intestinal- (hazard ratio = 0.516, P = 0.012) and diffuse-type (hazard ratio = 2.218, P = 0.016) gastric cancer." (PMID 23437057, 2013). "Clinicopathological characteristics of gastric cancer patients and the correlation with SP1 expression." (PMID 23437057, 2013). "In present study, the biological function of MTA2 protein in gastric cancer was assessed both in vitro and in vivo, the role of Sp1 in transcriptional regulation of human MTA2 gene promoter was also investigated." (PMID 24010737, 2013). "Metastasis-associated tumor gene family 2 (MTA2) and transcription factor specificity protein 1 (Sp1) expression were detected in 127 gastric cancer samples by immunohistochemistry staining." (PMID 24010737, 2013). "Intestinal type cells with reduced SP1 levels were more capable of migration and invasion than those with high SP1 expression; this result, in part, explains the decreased survival of patients expressing low levels of SP1 in intestinal-type gastric cancer." (PMID 23437057, 2013). "Further, Sp1/3 is constitutively overexpressed in pancreatic and gastric cancers and many signal transduction pathways terminating on Sp1-regulated genes are linked to cancer progression." (PMID 24324617, 2013). "Previous studies of SP1 in gastric carcinoma have concentrated on its direct association with VEGF and its involvement in angiogenesis during gastric carcinoma development." (PMID 23437057, 2013). "However, other mechanisms, such as migration, apoptosis, and cell cycle progression, may have been affected during tumor progression because gastric carcinoma is a disease caused by multiple factors, and SP1 is a transcriptional factor that interacts with many other genes." (PMID 23437057, 2013). "Our immunohistochemical data are consistent with previous clinicopathological studies demonstrating SP1 overexpression in gastric carcinoma tissues." (PMID 23437057, 2013). "Because aberrant expression of SP1 is related to cancer development and progression, we focused on SP1 expression in gastric carcinoma and its correlation with disease outcomes." (PMID 23437057, 2013).
gastric cancer (continued). "In recent studies, high SP1 and/or VEGF expression were associated with poor survival in human gastric carcinoma." (PMID 23437057, 2013). "This elevated Sp1 expression is inversely correlated with the survival of patients with gastric cancer." (PMID 19753117, 2009). "In summary, our findings demonstrated that PIK3CB and SP1 were co-overexpressed in gastric cancer." (PMID 38356702, 2024). "Previously, we demonstrated that andrographolide suppresses the lytic reactivation of EBV in gastric cancer cell lines by attenuating the expression of host transcription factors, SP1 and MEF2, via epigenetic modifications, especially through the function of HDAC6 and DNMT3A." (PMID 37958849, 2023). "TRIM25 promotes ubiquitination of Sp1 at K610 in gastric cancer." (PMID 37742010, 2023). "In addition, another study of gastric cancer indicated that SP1 promoted cancer growth and metastasis by transcriptionally activating the Oncostatin M receptor." (PMID 36964266, 2023). "Interestingly, ATF6 and SP1 RNA transcripts negatively correlated with ages in patients with gastric cancer." (PMID 37848946, 2023). "SP1 is reported to be a ferroptosis-related marker in gastric cancer." (PMID 36275721, 2022). "SP1 regulates MMRN1 expression in vitro in a gastric cancer model." (PMID 35132992, 2022). "It was also shown that the examined TF bound to construct with rs10815225 G allele but not to construct with C allele and that the up-regulation or silencing of SP1 resulted respectively in elevated or decreased PD-L1 expression on mRNA and protein level in SGC-7901 cells (gastric cancer cell line)." (PMID 33255938, 2020). "In fact, miR-23b was found to directly suppress expression of transcription factor SP1 in multiple myeloma cells, and in gastric cancer, an inhibiting effect of miR-223 on epithelial to mesenchymal transition via direct posttranscriptional silencing of SP1 was reported." (PMID 29720980, 2018). "Since Sp1 expression correlated with poor prognosis in gastric cancer, and our previous publication shows that triptolide can downregulate Sp1 leading to a decrease in HSP70 and HSF1, thereby causing cell death, we studied the expression of this protein in gastric cancer cells." (PMID 28192510, 2017). "It has also been reported that early stage gastric cancer is associated with weak or negative Sp1 expression whereas more advanced disease was associated with strong Sp1 expression." (PMID 28192510, 2017). "Previous studies have shown that Sp1 is an important regulator of angiogenesis in gastric cancer." (PMID 28192510, 2017). "Here, Sp1 was detected to be over-expressed in gastric cancer tissues." (PMID 29262634, 2017). "Here, we uncovered that, after binding to RAGE, AGEs upregulated Sp1 expression via activating MEK1/2/ERK pathway, while the treatment of MEK1/2 inhibitor, U0126, reduced the AGEs-induced Sp1 expression in gastric cancer cells by blocking the activation of ERK." (PMID 29262634, 2017). "Finally, the correlation between SENP3 and Sp1 levels was evaluated in the xenografts of human gastric cancers grown in the nude mice." (PMID 26511642, 2016). "Consequently, we divided intestinal- and diffuse-type gastric cancer cell lines into low- or high-SP1 expressor subtypes." (PMID 23437057, 2013). "Therefore, intestinal- and diffuse- type gastric cancer cells seem to have different migration/invasion signaling pathway and SP1 signaling is dependent on cell context." (PMID 23437057, 2013). "Given that Lauren's histological classification is significantly correlated with SP1 expression in gastric cancer, we divided the samples according to their histological type and analyzed their correlation with clinicopathological features as well as their relationship with overall patient survival." (PMID 23437057, 2013). "Both MTA2 and Sp1 protein had similar expression pattern in gastric cancer tissues." (PMID 24010737, 2013).
gastric cancer (continued). "Then, we sought to determine whether Sp1 played a role in regulating MMP-14 in gastric cancer cells." (PMID 23394613, 2013). "Concomitant expression of MTA2 and Sp1, and high GC-content sequence in proximal region of human MTA2 promoter, the potential Sp1 binding region, indicated that MTA2 might also be a downstream gene of Sp1 in gastric cancer." (PMID 24010737, 2013). "Concomitant expression of MTA2 and Sp1 was also observed in gastric cancer cell lines." (PMID 24010737, 2013). "Thus, the survival of gastric cancer patients was correlated not only with SP1 expression levels but also with the histological type." (PMID 23437057, 2013). "Here, we showed that Sp1 bound to the MMP-14 promoter in gastric cancer cells via ChIP assay." (PMID 23394613, 2013). "For example, Sp1 mRNA and DNA-binding activities are increased in epithelial tumors, suggesting that increased activity of this transcription factor contributes to tumor progression in the skin, and Sp1 has been shown to be constitutively overexpressed in pancreatic and gastric cancers." (PMID 21731707, 2011). "Besides, gastric cancer patients with higher expression of either ATF6 or SP1 had poor survival rates which suggested that these genes might act as a potential biomarker for diagnosis." (PMID 37848946, 2023). "Furthermore, in cisplatin-resistant gastric cancer tissues, it was found that low-SUMOylation of SP1 increased the expression of SP1 in gastric cancer tissues, and the increased SP1 promoted drug resistance of gastric cancer cells through the SNHG17/miR-23b-3p/Notch2 axis." (PMID 37777749, 2023). "Moreover, DYNC1I1 upregulation could also enhance its downstream TNPO2 expression through SP1 overexpression to promote the proliferation and invasion of gastric cancer cells." (PMID 35002514, 2022). "In addition, miR-502-5p inhibits cell growth by inhibiting SP1 in gastric cancer cells." (PMID 34288816, 2021). "Furthermore, Sp1 expression, but not Sp3, was frequently downregulated in gastric cancer compared with normal gastric mucosa, which was associated with a paralleled reduction in SHIP2 levels in gastric cancer." (PMID 28117748, 2017). "We next explored whether the expression levels of SENP3 correlated with the expression of Sp1 in human gastric carcinoma specimens using immunohistochemistry performed on the continuous sections of 21 surgically dissected tissues derived from gastric cancer patients." (PMID 26511642, 2016). "Survival analysis revealed that SP1 levels might become a prognostic biomarker of gastric cancer." (PMID 23437057, 2013). "For example, TRIM25 promotes SP1 ubiquitination at K610, further inhibiting the expression of MMP2 and angiogenesis in gastric cancer." (PMID 40796546, 2025). "JP3 (an antiangiogenic peptide) modulates the TRIM25/SP1/MMP2 axis to suppress tumor growth, metastasis, and angiogenesis in gastric cancer." (PMID 38955795, 2024). "Mechanistically, as an MMP2 targeting peptide, JP3 inhibits angiogenesis through TRIM25 (Tripartite motif containing 25)/SP1/MMP2 signaling, and plays a therapeutic role in gastric cancer." (PMID 36230577, 2022). "So, miR-1258 acted as a tumor suppressor to inhibit invasion and metastasis by targeting HPSE (heparanase) in gastric cancer and inhibited growth and EMT via targeting SP1 in oral squamous cell carcinoma." (PMID 35163224, 2022). "For example, miR-527 has been reported to be downregulated in gastric cancer and to inhibit cell proliferation, migration, and EMT by regulating Sp1." (PMID 35210429, 2022). "In gastric cancer, SP1 binds to the MTA2 gene promoter, up‐regulates MTA2 gene expression, and facilitates gastric cancer cell invasion and migration." (PMID 34185412, 2021). "Knockdown of SP1 downregulated CDCA3 expression, and the proliferation and invasion of gastric cancer cells is significantly inhibited." (PMID 34905505, 2021). "It is known that MIR335 negatively regulates the metastasis in gastric cancer by targeting BCL2L2 and SP1." (PMID 32582296, 2020).
gastric cancer (continued). "MiR-27b has also been shown to inhibit gastric cancer metastasis by targeting NR2F2, and suppress NSCLC invasion by targeting SP1." (PMID 31959200, 2020). "Other targets of MIR296 are the proto-oncogenes AKT2 in pancreatic cancer, PLK1 in non-small cell lung cancer, SP1 in cervical cancer and CDX1 in gastric cancer." (PMID 32582296, 2020). "In gastric cancer, MTA2 can be transcriptionally regulated by specificity protein 1 (Sp1), and MTA2 expression is closely related to tumour invasion, lymph node metastasis, and Tumor-Node-Metastasis (TNM) staging." (PMID 31771219, 2019). "To further confirm that triptolide induced gastric cancer cell death was mediated by inhibition of Sp1, we overexpressed Sp1 in MKN28 and MKN45 cell lines using a pCMV-Sp1 and treated them with 100nM triptolide." (PMID 28192510, 2017). "Screening several human gastric cancer cell lines, we found that the MKN45 and MGC803 lines exhibit marked differences in their SENP3 levels, and also had differences in their Sp1 levels (left)." (PMID 26511642, 2016). "For example, Sp1 positively regulates MTA2 and midkine (MDK) expressions in gastric cancer tissues 30 and glioma cells 29, respectively." (PMID 26763486, 2016). "In two previous studies, we showed that JWA inhibited oncogenic transcript factor Sp1, which in turn inhibited the MMP-2-dependent angiogenic potential of endothelial cells in gastric cancer and integrins αV and β3 in melanoma metastasis." (PMID 27167206, 2016). "In summary, we demonstrate, for the first time, that sub-cytotoxic MJ attenuates the MMP-14 expression via decreasing the Sp1 expression and binding on MMP-14 promoter, thus inhibiting the migration, invasion and angiogenesis of gastric cancer cells." (PMID 23394613, 2013). "In this study, we demonstrated the over-expressed Sp1 and its positive correlation with MMP-14 transcription in gastric cancer tissues." (PMID 23394613, 2013). "Sub-cytotoxic MJ attenuates the MMP-14 expression via decreasing the Sp1 expression and binding on MMP-14 promoter, thus inhibiting the migration, invasion and angiogenesis of gastric cancer cells." (PMID 23394613, 2013). "In gastric cancer, SP1 transcriptionally regulates ATXN2 expression, activating the PI3K/AKT signaling pathway, which contributes to ATXN2's anti-apoptotic and chemoresistant properties in gastric cancer." (PMID 39039334, 2024). "SP1‐activated lncRNA GCMA sponges miR‐124/34a and stimulates tumour metastasis of gastric cancer." (PMID 37929660, 2024). "SUMOylation inhibition of SP1 increases its expression level, which promotes the expression of LncRNA SNHG17 and alters the miR-23b-3p/Notch2 pathway, thus promoting the occurrence and development of gastric cancer." (PMID 37777749, 2023). "In addition to this, miR-502-5p was recently explored to target Sp1 transcription factor (SP1), thus impeding migration and invasion of gastric cancer cells." (PMID 35055115, 2022). "Mechanistically, JWA promotes the degradation of specificity protein 1 (SP1) through the ubiquitin-proteasome pathway and then inhibits the expression of its downstream pro-angiogenic factor MMP2, ultimately inhibiting the angiogenesis of gastric cancer." (PMID 36230577, 2022). "SP1, a member of the SP/Kruppel-like factor superfamily (Sp/KLF family) of transcription factors, has been reported to be highly expressed in pancreatic cancer, colorectal cancer, gastric cancer, and lung cancer." (PMID 33345272, 2021). "Furthermore, in gastric cancer CDCA3 expression is regulated by DNA methylation, and the binding activity of SP1 and the CDCA3 promoter is significantly up-regulated." (PMID 34905505, 2021). "In gastric cancer, AGAP2-AS1 is activated by SP1, promoting cell proliferation and invasion." (PMID 33889541, 2021). "Therefore, the signal shaft of circ_0005529/miR-527/Sp1 axis in GC was proposed and examined in cells and mouse models, which may provide promising therapeutic target for blocking gastric cancer growth and metastasis." (PMID 33472586, 2021).
gastric cancer (continued). "Furthermore, the correlation between DYNC1I1 and SP1, as well as TNPO2 and SP1 in gastric cancer was verified by the GEPIA website." (PMID 31605449, 2019). "Bae and colleagues provided a mechanistic insight, showing that BCL-W ectopic expression enhanced the invasive potential of gastric cancer and glioblastoma cell lines by inducing MMPs expression via a PI3K-AKT-mediated activation of SP1 and β-catenin, respectively." (PMID 29570632, 2018). "Similarly, overexpression of UCA1 induced by SP1 was reported to promote cell proliferation via recruiting EZH2 and activating AKT pathway in gastric cancer." (PMID 29719612, 2018). "Finally, correlation analysis revealed that FEZF1-AS1expression levels were positive correlation with SP1 and CDK2/CDK4/CDK6/CyclinD1 and inversely correlated with P21 expression levels in Gastric Cancer tissues." (PMID 28209170, 2017). "In summary, we show that XIAP-AS enhances XIAP transcription via interacting with Sp1 and that XIAP-AS may be a potential therapeutic target for gastric cancer." (PMID 28792527, 2017). "However, the pretreatment of RAGE-specific blocking antibody diminished AGEs-induced effects, which suggested that the AGEs-RAGE interaction increased the expression of Sp1 and MMP2 in gastric cancer cells." (PMID 29262634, 2017). "Overexpression of Sp1 could regulate the transcriptional activity of MTA2 promoter and might partially contribute to MTA2 expression in gastric cancer." (PMID 24010737, 2013). "Additionally, administration of sub-cytotoxic MJ attenuated the Sp1 expression and binding to MMP-14 promoter, implying the important role of Sp1 in sub-cytotoxic MJ-induced down-regulation of MMP-14 in gastric cancer cells." (PMID 23394613, 2013). "Importantly, there was a positive correlation between Sp1 protein and MMP-14 transcript levels in gastric cancer tissues." (PMID 23394613, 2013). "Specificity protein (Sp) transcription factors Sp1, Sp3 and Sp4 are overexpressed in colon and other cancer cell lines, and Sp1 is a negative prognostic factor for survival of pancreatic and gastric cancer patients." (PMID 21864401, 2011). "No mutations in the Sp1 element were detected, but one MSI positive colorectal and one MSI positive gastric cancer showed the A→G mutation, at the same site, IVS1 +681 bp in the MLH1 gene." (PMID 22022465, 2011). "CDCA3, through regulation by specificity protein 1 (SP1) and hypomethylation of its gene body, affects gastric cancer (GC) cell proliferation and invasion." (PMID 32716971, 2020). "Moreover, overexpression of Sp1 inhibited cell proliferation, induced apoptosis, suppressed cell motility and invasion in gastric cancer cells in vitro, which was, at least in part, due to transcriptional activation of SHIP2 mediated by Sp1, thereby inactivating Akt." (PMID 28117748, 2017). "Indeed, Sp1 levels and/or activities are increased in gastric cancer, breast carcinoma and pancreatic carcinoma compared with normal tissues." (PMID 19753117, 2009). "It was shown to be downregulated and might function as a tumor suppressor by targeting Myc, FSCN1 in gastric cancer, ZEB1 in oral squamous cell carcinoma, CRKL in hepatocellular carcinoma, TLN1 in nasopharyngeal carcinoma, AKT1 in melanoma, or BCL2 and SP1 in esophageal carcinomas." (PMID 33414893, 2020). "In addition, several reports have demonstrated the pro-survival and pro-carcinogenetic role of YY1, SP1 and HSF1 in gastric cancer (GC) development." (PMID 32751694, 2020).